IQANK1 (IQ motif and ankyrin repeat containing 1)
Synonyms: onco-lncRNA-3; CACClnc; FAM83H-AS1; FAM83HAS1
Tractability: No criterion of Open Targets' tractability assessment is met for any kind of drug.
Gene: Protein-coding gene on chromosome 8 (143,734,139 to 143,790,645, forward strand). Ensembl gene ENSG00000203499.
Genetic constraint (gnomAD): Loss-of-function variants: 20 observed, 13.53 expected, observed/expected ratio (o/e) 1.48, 90% interval 1.03 to 1.91. The upper end of that interval is the gene's LOEUF score, 1.91, which puts it in group 6 of 6, group 1 being the genes least tolerant of losing a copy. Missense variants: 161 observed, 150.34 expected, observed/expected ratio (o/e) 1.07, 90% interval 0.94 to 1.22. Synonymous variants: 64 observed, 60.72 expected, observed/expected ratio (o/e) 1.05, 90% interval 0.86 to 1.3.
Homologues: Orthologues: mouse Iqank1 (76% identical), guinea pig IQANK1 (75% identical), rat Iqank1 (74% identical), pig IQANK1 (72% identical). Paralogues in human: GABPB2 (15% identical), GABPB1 (13% identical).
Diseases named in the same sentence as IQANK1 in open-access papers:
IQANK1 is named in the same sentence as 4 diseases in open-access papers, as found by Europe PMC text mining. Sharing a sentence is not in itself a finding about the gene and the disease. The quoted sentences say what the papers report.
breast tumors (1 paper, 2019). "LINC00536 was found to be associated with expression of GSN and IQANK1, a ubiquitous actin filament-cleaving protein and a well-known downregulated target in breast tumors." (PMID 31850229, 2019).
IQANK1 also shares sentences with these, for which no sentence is quoted: cancer (1 paper); colorectal cancer (1); tumor (1).